MFF (mitochondrial fission factor)
Description:
Plays a role in mitochondrial and peroxisomal fission. Promotes the recruitment and association of the fission mediator dynamin-related protein 1 (DNM1L) to the mitochondrial surface. May be involved in regulation of synaptic vesicle membrane dynamics by recruitment of DNM1L to clathrin-containing vesicles (By similarity).
Synonyms: C2orf33; GL004; EMPF2
Tractability: Antibody: UniProt predicts a signal peptide or a membrane-spanning region. PROTAC: ubiquitination databases record sites on it; its protein half-life has been measured.
Gene: Protein-coding gene on chromosome 2 (227,325,151 to 227,361,188, forward strand). Ensembl gene ENSG00000168958.
Subcellular location: Mitochondrion outer membrane; Peroxisome; Cytoplasmic vesicle, secretory vesicle, synaptic vesicle
Subcellular location (Human Protein Atlas): Mitochondria; Principal piece
Gene Ontology:
Molecular function: identical protein binding; protein binding; protein homodimerization activity
Biological process: mitochondrial fission; mitochondrion organization; peroxisome fission; protein localization to mitochondrion; positive regulation of mitochondrial fission
Cellular component: mitochondrial membrane; mitochondrial outer membrane; mitochondrion; peroxisome; protein-containing complex; cytoplasm; synaptic vesicle
Genetic constraint (gnomAD): Loss-of-function variants: 10 observed, 27.22 expected, observed/expected ratio (o/e) 0.37, 90% interval 0.23 to 0.62. The synonymous counts are far from expectation, so gnomAD's model fits this gene poorly and the ratio says little. Missense variants: 303 observed, 330.24 expected, observed/expected ratio (o/e) 0.92, 90% interval 0.83 to 1.01. Synonymous variants: 83 observed, 112.28 expected, observed/expected ratio (o/e) 0.74, 90% interval 0.62 to 0.89.
Gene-disease validity (ClinGen):
ClinGen rates the evidence that MFF causes each of these diseases.
encephalopathy due to mitochondrial and peroxisomal fission defect (autosomal recessive): Moderate. A rare mitochondrial disease characterized by a variable phenotype comprising delayed psychomotor development or neurodevelopmental regression, hypotonia, seizures, microcephaly, optic atrophy, pyramidal signs, and peripheral neuropathy, among others.
Leigh syndrome (autosomal recessive): Moderate. A progressive neurological disease defined by specific neuropathological features associating brainstem and basal ganglia lesions.
Homologues: Orthologues: chimpanzee MFF (99% identical), macaque MFF (99% identical), rabbit MFF (98% identical), pig MFF (96% identical), mouse Mff (95% identical), rat Mff (94% identical), guinea pig MFF (93% identical), tropical clawed frog mff (68% identical), zebrafish mffb (55% identical), zebrafish mffa (47% identical), Drosophila melanogaster Tango11 (25% identical), Caenorhabditis elegans mff-2 (16% identical).
Diseases named in the same sentence as MFF in open-access papers:
MFF is named in the same sentence as 72 diseases in open-access papers, as found by Europe PMC text mining. Sharing a sentence is not in itself a finding about the gene and the disease. The quoted sentences say what the papers report.
breast cancer (9 papers, 2019 to 2026). A primary or metastatic malignant neoplasm involving the breast. "ACYP1 regulates glycolytic processes and is implicated in tumor growth, invasion, and resistance to apoptosis in liver cancer, while MFF plays a central role in mitochondrial fission and is implicated in lung, colon, and breast cancers by regulating cell proliferation, apoptosis, and invasion." (PMID 40503897, 2025). "Suppression of mitochondrial biogenesis by mitochondrial fission factor (MFF) has been proved to inhibit the activity of CSCs in breast cancer." (PMID 38561775, 2024). "Herein, we provide evidence that aberrant MFF expression in breast cancer cells drastically inhibits mitochondrial mass and function, associated with a reduction of mitochondrial oxidative metabolism and ATP depletion." (PMID 33194575, 2020). "Here, we have generated a mitochondrial fission factor (MFF)-overexpressing breast cancer cell line in order to dissect the role of aberrant mitochondrial fission in the maintenance and dissemination of breast CSCs." (PMID 33194575, 2020). "Moreover, mitochondrial fission factor (MFF) overexpression in breast cancer cells decreases both mitochondrial mass and activity." (PMID 34356350, 2021). "Nevertheless, the role of MFF in regulating mitochondrial dynamics in breast cancer has not been thoroughly elucidated." (PMID 33194575, 2020). "However, adaptor proteins for Drp-1 on the outer mitochondrial membrane like MID49/MIEF2 or FIS1, were found to be decreased in the basal-like subtype when compared to the other breast cancer subtypes, and no changes among the different subtypes were observed in MFF, another Drp-1 adaptor protein." (PMID 31231612, 2019). "In addition, the overexpression of MFF in breast cancer cells has a deleterious impact on the metabolic cell machinery, affecting OXPHOS, glycolysis, and CSC Activity, which indicates that improved mitochondrial fission may impair the metabolic processes required for breast cancer development." (PMID 36192752, 2022).
Encephalopathy (8 papers, 2020 to 2024). Encephalopathy is a term that means brain disease, damage, or malfunction. "MFF deficiency leads to mitochondrial Ca2+ overload, which triggers excessive ROS production, impedes mitochondrial biogenesis, and results in encephalopathy." (PMID 39916955, 2024). "Loss-of-function MFF mutations cause encephalopathy due to defective mitochondrial and peroxisomal fission 2 (EMPF2)." (PMID 35883852, 2022). "Biallelic pathogenic variants in MFF cause encephalopathy due to defective mitochondrial and peroxisomal fission 2 (EMPF2), a very rare disease associated with developmental delay, severe hypotonia, and abnormal signals in the basal ganglia." (PMID 35736332, 2022). "Human patients with pathogenic MFF variants suffer from ‘encephalopathy due to defective mitochondrial and peroxisomal fission 2’." (PMID 36085405, 2022). "Biallelic pathogenic variants in the MFF gene are recognized as the cause of the so-called “Encephalopathy due to defective mitochondrial and peroxisomal fission 2” (EMPF2; MIM#617086)." (PMID 33578638, 2021). "Rare recessive variants in MFF have been reported to give rise to epilepsy, encephalopathy, hypotonia, and Leigh syndrome." (PMID 33426505, 2020).
Obesity (4 papers, 2018 to 2023). Accumulation of substantial excess body fat. "In agreement with the activation of AMPK, other AMPK substrates, UNC-51-like kinase 1 (ULK1), and Mitochondrial fission factor (MFF) are increased in the liver of L-Ago2 KO mice, suggesting enhanced autophagy/mitophagy and improved mitochondrial quality in the Ago2-deficient liver in obesity." (PMID 30201950, 2018). "For example, CerS6 derived C16 sphingolipid has been shown to interact with mitochondrial fission factor (Mff), regulating mitochondrial dynamics and insulin resistance in obesity." (PMID 38078003, 2023). "In particular, hepatic Cer 16:0, specifically formed by CerS6, but not by CerS5, binds to mitochondrial fission factor (MFF), which, activated, promotes mitochondrial fission, causing mitochondrial dysfunction, an event that has been related to insulin resistance and obesity." (PMID 37108620, 2023). "Moreover, CerS6-derived C16:0 sphingolipids, but not CerS5-derived, can interact with the mitochondrial fission factor (Mff) and promote mitochondrial fission and insulin resistance in obesity." (PMID 32121501, 2020).
diabetes (3 papers, 2021). "Although the expression level of mitochondrial fission factor was also reduced in the Drp1cKO mice compared with the WT mice, its expression was not affected by the induction of diabetes." (PMID 33953167, 2021).
neuroblastoma (3 papers, 2018 to 2022). Neuroblastoma (NB) is the most common solid, extracranial childhood tumor. "As a positive control to show that the MFF S146 site is regulated by AMPK activation, we overexpressed the human isoform of MFF in Neuro2A (N2A) neuroblastoma cells and treated with Metformin, a potent activator of AMPK40, or a vehicle control." (PMID 35915085, 2022). "MFF isoform 2 is a dominant isoform of MFF that is commonly expressed in various cell types, including epithelial cells, fibroblasts, prostate cancer cells and neuroblastoma cells as well as in the brain." (PMID 34745083, 2021). "Moreover, neuronal cancer cell lines that lacked TRAP1 such as neuroblastoma and glioma showed irregular mitochondrial morphology with diminished levels of dynamin-related protein 1 (Drp1) and mitochondrial fission factor (Mff)." (PMID 30158430, 2018).
optic atrophy (3 papers, 2018 to 2024). A disorder characterized by loss of optic nerve fibers. "Mutations in DRP1 lead to several serious neurological disorders including epileptic encephalopathy and optic atrophy, A truncating mutation in MFF was first described in a Saudi Arabian child with developmental delay, pyramidal signs, and neuropathy." (PMID 29361167, 2018).
Autoimmunity (2 papers, 2020 to 2022). The occurrence of an immune reaction against the organism's own cells or tissues. "In addition, besides MNRR1, a number of other nDNA-encoded mitochondrial proteins such as GSTP1, PINK1, SPATA5 and MFF have been implicated in BC progression or BC risk, suggesting that mitochondrial autoimmunity prominently participates in breast carcinogenesis." (PMID 33615312, 2020).
diabetic nephropathy (2 papers, 2023 to 2024). "Lower levels of DUSP1 activate c-Jun N-terminal kinases (JNK), which selectively phosphorylates mitochondrial fission factor (Mff), exacerbates oxidative stress, and accelerates apoptotic cell death in diabetic nephropathy." (PMID 36818747, 2023).
dilated cardiomyopathy (2 papers, 2021 to 2025). Cardiomyopathy which is characterized by dilation and contractile dysfunction of the left and right ventricles. "Intriguingly, while MFF -/- mice died at ~13 weeks from dilated cardiomyopathy caused heart failure, when crossed with MFN1 -/- mice, which die at embryonic stage, the double MFF -/-; MFN1 -/- mice do considerably better." (PMID 33810506, 2021). "In experimental models, inhibition of mitochondrial fission and mitophagy by knocking down Drp1 or Mff (mitochondrial fission factor) has led to dilated cardiomyopathy." (PMID 40114920, 2025).
hepatocellular carcinoma (2 papers, 2021 to 2025). A malignant tumor that arises from hepatocytes. "Mitochondrial fission factor (MFF) is upregulated in hepatocellular carcinoma (HCC) CSCs where it promotes mitochondrial fission and increases tumor-initiating potential." (PMID 40801609, 2025).
melanoma (2 papers, 2020). A malignant, usually aggressive tumor composed of atypical, neoplastic melanocytes. "Further, a recent study demonstrated the therapeutic relevance of targeting mitochondrial fission factor DRP1 in BRAFV600E melanoma; however, it didn’t show any metabolic correlation despite a more glycolytic nature of BRAFV600E cancers." (PMID 33738242, 2020).
memory impairment (2 papers, 2022). "In conclusion, the homologous mutation in the Timm8a1 gene caused the hearing impairment, memory impairment, and anxiety-like behavior, and the latter two phenotypes may be correlated with reduced mitochondrial size regulated by upregulation levels of mitochondrial fission factor, MTFP1." (PMID 36090790, 2022).
ovarian carcinoma (2 papers, 2023 to 2025). A malignant neoplasm originating from the surface ovarian epithelium. "Finally, the study shows that MFF is highly expressed in ovarian cancer cells and that high MFF expression is associated with poor prognosis in patients with ovarian cancer." (PMID 37291333, 2023). "Similar to the ovarian cancer cell line results, the expression of MFF and CPT1A showed a high positive correlation." (PMID 37291333, 2023). "Together, these results further demonstrate that CPT1A regulates mitochondrial dynamics by regulating MFF expression, which in turn promotes mitochondrial function and cell growth in ovarian cancer cells." (PMID 37291333, 2023). "Knockdown of MFF significantly inhibited the growth and proliferation of ovarian cancer cells in vitro and in vivo, indicating that MFF can be a therapeutic target for ovarian cancer therapy." (PMID 37291333, 2023). "The high expression of MFF in ovarian cancer promotes mitochondrial fission and enhances mitochondrial function, thereby promoting the development of ovarian cancer." (PMID 37291333, 2023). "To further examine the role of MFF in the onset and development of ovarian cancer, we next examined the effect of MFF knockdown on the tumorigenesis of SKOV-3 cells in nude mice." (PMID 37291333, 2023). "MFF inhibition significantly inhibits the progression of ovarian cancer in vivo." (PMID 37291333, 2023). "In addition, IHC staining showed that the positive rate of Ki-67 in tumor cells of the MFF knockdown group was significantly lower, meanwhile the expression of p21 was increased, indicating that MFF played a role in promoting carcinogenesis in ovarian cancer." (PMID 37291333, 2023). "The results suggest that the expression of MFF in ovarian cancer patients correlates with poor clinical outcomes and that MFF could serve as an important prognostic marker." (PMID 37291333, 2023). "We found that Parkin knockdown significantly inhibited the ubiquitination of MFF, while knockdown of March5 had little effect on the ubiquitination of MFF, indicating that Parkin may mediate MFF ubiquitination in ovarian cancer cells." (PMID 37291333, 2023). "In this study, we confirmed that MFF is highly expressed in ovarian cancer cells." (PMID 37291333, 2023). "Furthermore, Kaplan-Meier survival analysis from the TCGA data showed that ovarian cancer patients with high MFF expression correlated with a significantly shorter overall survival (p = 0.0017) and a shorter Progression-free survival (p = 0.031) than those with low MFF expression." (PMID 37291333, 2023). "In ovarian cancer, CPT1A promoted the succinylation of mitochondrial fission factor (MFF) at K302 to regulate mitochondrial fission and function and promoted the growth and proliferation of ovarian cancer cells." (PMID 39781339, 2025). "Our study futher shows that CPT1A regulates mitochondrial fission and function through mitochondrial fission factor (MFF) to promote the growth and proliferation of ovarian cancer cells." (PMID 37291333, 2023). "We detected the protein expression of CPT1A and MFF in ovarian cancer cell lines and found that CPT1A and MFF were indeed positively correlated at the protein level." (PMID 37291333, 2023).
prostate carcinoma (2 papers, 2021). A carcinoma that arises from epithelial cells of the prostate gland. "Paradoxically, deficiency or silencing of MFF also induced apoptosis in cardiomyocytes, HeLa, prostate cancer and KRAS-transformed salivary duct cancer cells." (PMID 34745083, 2021). "In prostate cancer, c-Myc has been shown to regulate cancer metastasis via regulating mitochondrial trafficking and to control mitochondrial fission via upregulating the mitochondrial fission factor (MFF)." (PMID 33947138, 2021).
sarcopenia (2 papers, 2022). Progressive decline in muscle mass due to aging which results in decreased functional capacity of muscles. "Hence, reductions of mitochondrial fission proteins (such as DRP1, MFF, and FIS1) in patients with sarcopenia inhibit mitophagy and leads to the accumulation of dysfunctional organs and muscle atrophy." (PMID 36561214, 2022).
tongue squamous cell carcinoma (2 papers, 2015 to 2025). A squamous cell carcinoma that arises from the tongue. "Here, we show that MFF mediated mitochondrial fission and apoptosis in tongue squamous cell carcinoma (TSCC) cells after cisplatin treatment and that miR-593-5p was downregulated in this process." (PMID 25912308, 2015). "In tongue squamous cell carcinoma (TSCC), mitochondrial fission factor (MFF) mediates both mitochondrial fission and apoptosis following cisplatin treatment." (PMID 41573644, 2025).
bone osteosarcoma (1 paper, 2021). A usually aggressive malignant bone-forming mesenchymal neoplasm arising from the bone. "Next, we used siRNAs to deplete DRP1, MFF, Mid51 or CTRP1 from human bone osteosarcoma (U2OS) cells." (PMID 34837016, 2021).
cardiomyopathy (1 paper, 2020). A disease of the heart muscle or myocardium proper. "MFF-null mice display neuromuscular defects and cardiomyopathy, leading to heart failure, and die at an average age of 13 weeks." (PMID 32714603, 2020). "Remarkably, crossing MFF−/− with Mfn1−/− mice, both lethal on their own, rescued the cardiomyopathy, mitochondrial defects and oxidative stress." (PMID 32714603, 2020).
colon cancer (1 paper, 2022). "Tan IIA regulates mitochondrial fission through the JNK/mitochondrial fission factor (MFF) axis, which in turn upregulates mitochondrial pro-apoptotic proteins (Bax and Bad), activates caspase 9, and leads to colon cancer SW837 cell apoptosis." (PMID 36172186, 2022).
dominant optic atrophy (1 paper, 2017). "For instance, mutations in MFN2, OPA1, DNM1L, and MFF (encoding mitochondrial fission factor) cause Charcot–Marie–Tooth disease type 2A (MIM# 609260), dominant optic atrophy (MIM# 165500), and severe infantile encephalomyopathies (MIM# 614388; 617086), respectively." (PMID 28544275, 2017).
glioma (1 paper, 2024). A benign or malignant brain and spinal cord tumor that arises from glial cells (astrocytes, oligodendrocytes, ependymal cells). "Subsequently, we validated the regulatory functions of DNM1L/DRP1, FIS1, and MFF in autophagic flux and mitophagy within GSCs by conducting analogous treatment experiments, yielding results consistent with those observed in glioma cell lines." (PMID 39350223, 2024).
infarction (1 paper, 2024). A localised pathological necrosis of tissue resulting from obstruction of the blood supply usually by a thrombus, an embolus, or vascular torsion. "Moreover, in mice with I/R injury, mitochondrial fission factor (Mff) is significantly increased, whereas mice with Mff gene knockout show a significant reduction in the infarction area and recovery of cardiac ejection function." (PMID 39247823, 2024).
leukemia (1 paper, 2024). A malignant (clonal) hematologic disorder, involving hematopoietic stem cells and characterized by the presence of primitive or atypical myeloid or lymphoid cells in the bone marrow and the blood. "In line, VEN-resistant leukemia was characterized by larger and elongated mitochondria, lower expression levels of the mitochondrial fission factor DRP1 and significantly higher mitochondrial DNA content, further corroborating our finding of augmented mitochondrial metabolism in VEN-resistant ALL." (PMID 38961053, 2024).
lung fibrosis (1 paper, 2023). "To evaluate whether the DRP1/MFF-dependent fission pathway is activated in lung (myo)fibroblasts in experimental lung fibrosis, we treated wild-type C57BL/6 mice with bleomycin via oropharyngeal aspiration." (PMID 36422990, 2023). "Expression of DRP1 and MFF is elevated in lung myofibroblasts in both human IPF and bleomycin injury–induced mouse lung fibrosis." (PMID 36422990, 2023). "Importantly, we found that the DRP1/MFF pathway is activated in fibrotic lung myofibroblasts in both human IPF and bleomycin-induced mouse lung fibrosis." (PMID 36422990, 2023).
metastatic cancer (1 paper, 2022). A carcinoma which has spread from the original site of growth to another anatomic site. "We found that MFF is a direct transcriptional target of oncogenic Myc and is overexpressed in primary and metastatic cancer compared with normal tissue, suggesting that increased MFF expression contributes to tumor malignancy." (PMID 35269393, 2022).